INS (insulin)
Diseases named in the same sentence as INS in open-access papers (continued):
Sharing a sentence is not in itself a finding about the gene and the disease.
anemia (continued). "Furthermore, participants who used a combination of insulin and oral GLDs or used insulin separately were more likely to have anemia compared to those who were treated with oral GLDs only." (PMID 36894956, 2023). "In iron deficient women without anaemia, intravenous administration of 1000 mg of iron in a single sitting did not impair glucose-induced insulin secretion despite a transient increase in the levels of circulating reactive oxygen species." (PMID 35706490, 2022). "Adverse effects of ADT include decreased bone mineral density; metabolic changes such as weight gain; decreased muscle mass and increased insulin resistance; decreased libido and sexual dysfunction; hot flashes; gynecomastia; reduced testicle size; anemia; and fatigue." (PMID 30862069, 2019). "A high iron store may mask the actual effect of correction of anemia on insulin sensitivity and b-cell function." (PMID 28739553, 2018). "CPSF6 indirectly modulates glucose homeostasis and insulin secretion, while HBA2, a commonly known marker for anemia and β-thalassaemia, interferes with glycemic markers in T2DM patients." (PMID 37686344, 2023). "Multivariate logistic regression analysis showed that anemia, myosteatosis, higher postoperative capillary blood glucose (CBG) before TNA infusion, and insulin in the TNA were independent influencing factors for severe HG." (PMID 35237639, 2022). "Signaling pathways including AMPK, mitophagy, adenine ribonucleotide biosynthesis, pyrimidine metabolism, insulin related PI3K-Akt and FOXO, anemia, ferroptosis, and fatty acid metabolism were less down-regulated." (PMID 34679790, 2021). "Although the underlying mechanisms linking anaemia and GDM are still unknown, various mechanisms have been suggested such as iron being a catalyst of several biochemical reactions leading to production of reactive oxygen species which can decrease insulin sensitivity." (PMID 32365670, 2020). "The severe anemia group also had significantly higher levels of cord blood prolactin, insulin, and placental lactogen compared to the moderate anemia group, but these were not significantly different from the non-anemic group." (PMID 37764824, 2023).
Hirsutism (92 papers, 2009 to 2026). Abnormally increased hair growth referring to a male pattern of body hair (androgenic hair). "Adjusted logistic regression models showed an insignificant association between diabetic female hirsutism and insulin intake (OR = 1.1 and 1.0, respectively; P > 0.05)." (PMID 36654645, 2022). "In this study, we aim to assess insulin therapy as a risk factor for hirsutism among women with T1DM and T2DM in Saudi Arabia." (PMID 36654645, 2022). "Elevated insulin levels can directly stimulate the production of ovarian androgen, and elevated androgen levels can cause menstrual disorders, hirsutism, ovarian cysts, ovarian fibrosis and other PCOS-related diseases." (PMID 33638949, 2021). "Flutamide significantly reduces both fasting insulin secretion and insulin response during oral glucose tolerance testing, but only in women with idiopathic hirsutism." (PMID 41440753, 2025). "There was conversely an improvement in waist circumference, waist/hip ratio, hirsutism, fasting insulin, total cholesterol and LDL‐c; these studies again included women of any age and BMI and were noted to have a serious risk of bias across reported outcomes." (PMID 41035114, 2025). "Lowering these metabolic disruptions improved insulin sensitivity and reduced androgen levels, alleviating symptoms such as irregular menstrual cycles, hirsutism, and improving ovarian morphology." (PMID 39896947, 2025). "Studies have shown that metformin not only improves insulin sensitivity but also reduces hirsutism severity." (PMID 40337376, 2025). "In meta-analysis, bariatric surgery has been associated with improvements in total testosterone levels, fasting blood glucose, and insulin, along with significant reductions in triglycerides, self-reported acne, and hirsutism." (PMID 41295220, 2025). "The ORs were calculated for oligoovulation, hirsutism, and elevated 60-minute postload insulin levels." (PMID 36568921, 2022). "The outcome parameters were change in weight, luteinizing hormone (LH)/follicle stimulating hormone (FSH) ratio, hirsutism, blood glucose and insulin levels, HOMA-IR, and lipid profile." (PMID 36420435, 2022). "There was a case of a 12-year-old female with insulin-mediated pseudoacromegaly showing AN, hirsutism, and acromegaly-like appearance." (PMID 36292208, 2022). "A male newborn with acanthosis nigricans, hirsutism, high insulin levels, and intrauterine growth retardation was compound heterozygous for c.3196C > T (p.R1066*) and c.3614C > T (p.Q1232*) in the tyrosine kinase domain of the β-subunit in INSR." (PMID 33663443, 2021). "Our clinical and biochemical parameters confirmed that women with PCOS, had higher scores in terms of WHR, hirsutism, diastolic blood pressure, insulin, HOMA-IR, hsCRP, total cholesterol, LDL-C, total testosterone, and LH but also lower HDL-C values." (PMID 29631598, 2018). "For instance, diazoxide—a potassium channel opener that inhibits insulin secretion from pancreatic β‐cells—is widely used as a first‐line agent, although its use may be limited by side effects such as fluid retention and hirsutism." (PMID 40124204, 2025). "Metformin, oral contraceptives, gonadotropin-releasing hormone (GnRH) antagonists, and other alternatives, including finasteride, eflornithine, fibroblast growth factors (FGFs), and vitamin D, are all shown to help improve insulin sensitivity and regulate menstrual cycles and reduce hirsutism." (PMID 38595887, 2024). "Metformin may also reduce hirsutism through improvement in hyperandrogenaemia and probably by reducing circulating insulin levels." (PMID 36994287, 2023). "Finally, to study the effect of insulin therapy on the development of hirsutism, a logistic regression analysis was conducted adjusted for age, type and duration of DM, PCOS, and BMI." (PMID 36654645, 2022).
Hirsutism (continued). "The mechanisms by which insulin resistance impacts the hormonal system are numerous, moreover, it has been shown that insulin induces elevated androgen production and produces a hormonal milieu which results in hirsutism." (PMID 31611740, 2019). "As expected PCOS women (from both centers) had less number of menstrual cycles per year, had more severe hirsutism, elevated serum total testosterone, fasting plasma glucose, and insulin levels as compared to healthy controls, which is in accordance with previously published literature." (PMID 31781027, 2019). "Oner and muderris showed ω-3 also may be effective in decreasing hirsutism, BMI, LH, testosterone, insulin, Homeostatic model assessment (HOMA) levels, and increasing Sex hormone-binding globulin (SHBG) and TNF-α in women with PCOS." (PMID 25653669, 2015). "PCOS patients presented with increased hirsutism scores, waist-to-hip ratio, fasting insulin and triglycerides, serum concentrations of total and free testosterone, androstenedione, 17-hydroxyprogesterone, dehydroepiandrosterone-sulfate and luteinizing-hormone." (PMID 19440331, 2009). "Our findings also revealed a notable negative correlation between EPI and BMI, waist circumference, Ferriman–Gallwey hirsutism scores, HOMA-IR, fasting glucose, triglycerides, fasting insulin, and testosterone." (PMID 40638469, 2025). "Anti-androgens such as finasteride, flutamide, spironolactone, or bicalutamide, along with lifestyle modifications, are more effective in improving hirsutism, SHBG, fasting insulin, and the fasting insulin:glucose ratio." (PMID 39749338, 2024). "Metformin increases insulin sensitivity and improves ovulatory function in PCOS, whereas androgen levels and hirsutism scores are only mildly improved." (PMID 35740476, 2022). "The primary outcomes to be considered were follicular count, hirsutism, total testosterone levels, free androgen index (FAI), and insulin sensitivity (HOMA-IR), and the secondary outcome was the anti-Müllerian hormone (AMH) level." (PMID 36120462, 2022). "Since the insulin sensitizing agent metformin has been reported to decrease BMI and testosterone levels in PCOS women, its application to reduce hirsutism merits further exploration." (PMID 33794861, 2021). "Metformin has been shown to be as effective in the management of hirsutism as the COCP, and was superior to the COCP for controlling weight related symptoms and glucose and insulin dysregulation, but the COCP was superior for menstrual regulation." (PMID 31581747, 2019). "They reported a significant decrease in fasting plasma glucose, serum insulin, HOMA-IR, TT, FAI, and hirsutism as well as a significant increase in SHBG and total antioxidant capacity in the group receiving 4000 IU of cholecalciferol daily." (PMID 29946756, 2019). "PCOS symptoms like weight, hirsutism, irregularity ofperiods and ovulation symptoms were taken care off and decreases inweight, no cyst formation, Decreases Serum Insulin levels, Decreasesright and left ovary volume (Pandyaet al., 2015)." (PMID 40372207, 2025). "Furthermore, supplementation significantly reduced serum insulin, HOMA-IR, TT, FAI, and hirsutism and increased SHBG." (PMID 38994457, 2024). "It was found that insulin therapy does not have either a positive or negative effect on hirsutism as an outcome (OR = 1.0, 95% CI: 0.38-2.1)." (PMID 36654645, 2022). "Moreover, it was negatively correlated to its target gene; ET-I as well as fasting serum insulin (FSI), HOMA-IR, PCOS phenotype; hirsutism score, ovarian volume and antral follicle count (AFC)." (PMID 31064393, 2019). "Abnormal insulin dynamics are frequently established by the time phenotypic features of PCOS (hirsutism, cystic acne) emerge in late adolescence, irrespective of subject BMI." (PMID 21899727, 2011).
Hirsutism (continued). "In a meta-analysis reviewing vitamin E supplementation in women with PCOS, vitamin E was associated with reduced fasting glucose and insulin levels, HOMA-IR, total cholesterol, triglycerides, and total testosterone and an increase in SHBG without a significant difference in HLD, BMI, and hirsutism." (PMID 41295220, 2025). "In brief, insulin may exert its role in hyperandrogenism in PCOS pathophysiology via two distinct pathways: 1) stimulation of androgen production of theca cells with luteinizing hormone (LH) and increased androgen production which results in hirsutism and infertility." (PMID 31611740, 2019). "The benefits to adults with PCOS in improving hirsutism scores, menstrual cyclicity, and metabolic status depends on whether metformin is used as monotherapy or in combination with anti-androgen and/or OCP, as well as the insulin sensitivity status of the patient." (PMID 21899727, 2011). "Significant effects of metformin on hirsutism scores and ovulation were found in lean, hyperinsulinemic women with PCOS, and a decrease in DHEA-S levels in lean PCOS, regardless of insulin levels." (PMID 21899727, 2011). "A large, multi-centric, randomized, controlled study on 1000 patients with PCOS, undergoing ovulation induction, found that AN, as well as BMI, WC, and menstrual cycle anomalies correlated with fasting insulin and HOMA-IR, whereas hirsutism and acne score did not." (PMID 36292208, 2022).
nonalcoholic steatohepatitis (92 papers, 2011 to 2025). "Increased PBA/SBA ratio has been associated with decreased insulin sensitivity in patients with NAFLD or nonalcoholic steatohepatitis." (PMID 35670534, 2022). "Pharmacologic inhibition of PASK also confirmed its capacity for improving insulin sensitivity, reducing nonalcoholic steatohepatitis caused by an HFD." (PMID 34444712, 2021). "Some investigators have reported a significant association between dSAT and insulin sensitivity, non-alcoholic steatohepatitis, and adverse lipid and glycemic profiles." (PMID 26877772, 2016). "When assessed at a tissue-specific level, subcutaneous adipose tissue in the nonalcoholic steatohepatitis patients exhibits IR, with much insulin (>6-fold) to cause less suppression of glycerol release (1/2-maxima level), even seriously than that of liver and skeleton muscle." (PMID 28695131, 2017). "This study aimed to evaluate the therapeutic effects of salidroside on nonalcoholic steatohepatitis (NASH) in rats and explore the underlying mechanisms related to insulin signaling." (PMID 28255329, 2017). "This study was conducted to evaluate the therapeutic effects of salidroside on high-fat-diet-induced nonalcoholic steatohepatitis (NASH) in rats and to explore the underlying mechanisms pertaining to insulin signaling." (PMID 28255329, 2017). "FGF15/19 efficiently increases insulin sensitivity and is currently utilized to treat major metabolic illnesses such as diabetes, obesity, and non-alcoholic steatohepatitis (NASH)." (PMID 40599770, 2025). "Early reports indicate that UDCA improves glucose metabolism; that is, administration of high-dose UDCA improves glycemic parameters, insulin sensitivity, and insulin resistance surrogate markers in patients with nonalcoholic steatohepatitis." (PMID 38455850, 2024). "For example, the epigallocatechin-3-gallate supplement has been shown to improve insulin sensitivity and promote the functional recovery of insulin receptor substrate-1 in a model of nonalcoholic steatohepatitis." (PMID 37242133, 2023). "In vivo, CD53 deletion in nonalcoholic steatohepatitis diet-fed mice blocked peripheral adipose accumulation and adipose inflammation, insulin tolerance, and liver lipid accumulation." (PMID 36581203, 2023). "Pioglitazone is known to improve insulin sensitivity that results in decreasing serum fatty acids and resolution of non-alcoholic steatohepatitis." (PMID 34858740, 2021). "The ability of pioglitazone in improving insulin sensitivity has resulted in decreased blood glucose, serum fatty acids, and the resolution of non-alcoholic steatohepatitis in patients with type 2 diabetes or prediabetes, as well as nondiabetic patients." (PMID 34858740, 2021). "Mimicking insulin signal in the liver, loss of hepatic PTEN resulted in non-alcoholic steatohepatitis (NASH) while suppressing gluconeogenesis." (PMID 30038596, 2018). "These insulin-sensitizing agents have additionally shown promise for the treatment of biopsy-proven non-alcoholic steatohepatitis in small clinical trials." (PMID 21960993, 2012). "Pioglitazone also has shown improvement in liver injury and inflammation in patients with non-alcoholic steatohepatitis and this has been attributed to the beneficial effects of Pioglitazone on insulin signaling." (PMID 22412837, 2012). "It has been demonstrated that leptin could play an important role in the progression of nonalcoholic steatohepatitis by promoting liver lipid decomposition and increasing insulin sensitivity in the early stage." (PMID 35896788, 2022). "Moreover, LCN2 deletion improved insulin sensitivity in adipose tissue of diet-induced obesity or attenuated non-alcoholic steatohepatitis (NASH) progression in the liver of methionine- and choline-deficient-diet mice." (PMID 36501079, 2022).
nonalcoholic steatohepatitis (continued). "In addition, a study has suggested that patients with nonalcoholic steatohepatitis and chronic hepatitis C virus infection have impaired insulin signaling and increased cell apoptosis in the liver." (PMID 35142592, 2022). "The traditional treatment includes pioglitazone, a type of insulin-sensitizing agent, which could improve liver biochemical and histological parameters in patients with nonalcoholic steatohepatitis (NASH)." (PMID 27872642, 2016). "In addition, several studies have also demonstrated the important role of Socs3 in the pathogenesis of nonalcoholic steatohepatitis, regulating insulin sensitivity, leptin signaling, glucose metabolism, lipogenesis, and fatty liver." (PMID 25617409, 2015). "Western diet (WD)-fed MC4R-KO mice and Gubra-Amylin non-alcoholic steatohepatitis (GAN) diet-fed mice models have been reported to highly resemble human MASH in terms of obesity, dyslipidemia, insulin resistance, liver injury, steatosis, and fibrosis." (PMID 41266634, 2025). "We observed that SERPINA12 expression was significantly increased in nonalcoholic steatohepatitis (NASH) patients compared with an in vitro human liver model (a condition of low glucose and low insulin to mimic the healthy liver)." (PMID 38332150, 2024). "The progression of NAFLD towards non-alcoholic steatohepatitis (NASH) is driven by multiple insults, including insulin resistance, hormones secreted from the adipose tissue, dietary components, gut microbiota and genetic pathways." (PMID 37492223, 2023). "Different treatments to address non-alcoholic steatohepatitis (NASH) include PUFA supplements, vitamin E, and insulin sensitizing agents with a focus on pioglitazone and statin agents." (PMID 36771772, 2023). "In patients with non-alcoholic fatty liver (NAFL) and non-alcoholic steatohepatitis (NASH), a significant decrease in mitochondrial maximal respiratory capacity was observed, along with decreased insulin sensitivity." (PMID 37920803, 2023). "Using the ligand of FXR named obeticholic acid (OCA) has been proven to improve insulin sensitivity in phase II and III trials in patients with nonalcoholic steatohepatitis (NASH)." (PMID 37630619, 2023). "Insulin sensitivity was improved in the ADAMTS5-J KO mice, and they were protected against non-alcoholic steatohepatitis in the DIO model (as the ADAMTS5-P mice)." (PMID 29293679, 2018). "For example, nonalcoholic steatohepatitis patients treated with high-dose UDCA experienced significant reductions in serum glucose, glycosylated hemoglobin, and serum insulin levels." (PMID 23450079, 2013). "An important role in the development of steatosis and its progression to non-alcoholic steatohepatitis is played by the ghrelin-ghrelin O-acyltransferase (GOAT) system which is involved in energy and lipid metabolism, insulin resistance, inflammation and apoptotic cell death." (PMID 41441034, 2025). "Hence, medications possess potential pharmacodynamics to increase insulin sensitivity, congregating much attention for utilization for NAFLD or non-alcoholic steatohepatitis (NASH) (the most severe form of NAFLD)." (PMID 39421288, 2024). "KCTD17 expression is increased in the livers of obese mice and patients with NAFLD/nonalcoholic steatohepatitis (NASH), leading to the degradation of pleckstrin homology domain leucine-rich repeat protein phosphatase 2 (PHLPP2) to prolong insulin signaling by dephosphorylating AKT97." (PMID 37779139, 2023). "However, some insulin sensitizers cannot improve NAFLD, especially nonalcoholic steatohepatitis (NASH)." (PMID 36059948, 2022). "PM2.5 exposure induces integrated oxidative stress, endoplasmic reticulum (ER) stress, and inflammatory responses in the liver, leading to a non-alcoholic steatohepatitis (NASH)-like phenotype, characterized by hepatic steatosis, inflammation, fibrosis, and insulin resistance, in animal models." (PMID 29176715, 2017).